TRIM32 (tripartite motif containing 32)
Diseases named in the same sentence as TRIM32 in open-access papers (continued):
Sharing a sentence is not in itself a finding about the gene and the disease.
neuroblastoma (8 papers, 2015 to 2023). Neuroblastoma (NB) is the most common solid, extracranial childhood tumor. "In a murine neuroblastoma model TRIM32 enhances differentiation by catalyzing the addition of stabilizing ubiquitin chains (linkage type not defined) to the retinoic acid receptor (RARα), a factor that has well-known roles in neuronal differentiation." (PMID 38115822, 2023). "Tripartite motif-containing 32 (TRIM32) was identified as an ACD inducer in human neuroblastoma cells." (PMID 33194665, 2020). "In neuroblastoma, TRIM32 interacts with MYCN and promotes its proteasomal degradation, which induces asymmetric cell division." (PMID 33173411, 2020). "We recently reported that TRIM32 promoted the proteasomal degradation of MYCN at spindle poles during cell division, while TRIM32 overexpression induced ACD in human neuroblastoma cells." (PMID 33194665, 2020). "In an intriguing parallel with normal neurogenesis, in neuroblastoma-initiating cells TRIM32 binds and ubiquitinates another MYC family member, N-MYC, at spindle poles during mitosis to drive asymmetric cell division that eventually results in tumor cell death." (PMID 38115822, 2023). "TRIM32 overexpression promotes cell proliferation, transforming activity, cell motility and prevents apoptosis, but it is also shown to promote asymmetric cell division of neuroblastoma cells and to enhance TNFα-induced apoptosis." (PMID 33999923, 2021). "Interestingly, also TRIM32 has recently been shown to regulate N-Myc in human neuroblastoma cells by ubiquitinating it at spindle poles during mitosis, thereby targeting it for proteasomal degradation and inducing asymmetric cell division." (PMID 29899379, 2019). "Izumi et al19 reported that TRIM32 has the capacity to up‐regulate asymmetric cell division, which works against MYCN and can be considered a tumour suppressor in human neuroblastoma cells." (PMID 30079558, 2018). "Each construct was then transfected into neuroblastoma (N2a) cells together with DDX6, TRIM32 or both." (PMID 25722370, 2015).
Bardet-Biedl syndrome (6 papers, 2020 to 2024). A ciliopathy with multisystem involvement. "Furthermore, a number of other UPS proteins have been implicated in ciliopathies including TOPORS, an E3 ligase located at the basal body and cilium that is mutated in retinitis pigmentosa (RP), and TRIM32, an E3 mutated in Bardet-Biedl syndrome (BBS)." (PMID 35170427, 2022).
Alzheimer disease (5 papers, 2016 to 2022). A progressive, neurodegenerative disease characterized by loss of function and death of nerve cells in several areas of the brain leading to loss of cognitive function such as memory and language. "TRIM32 has been implicated in various neurological disorders, such as depression, Alzheimer’s disease, autism spectrum disorder, or attention deficit hyperactivity disorder." (PMID 35796533, 2022). "TRIM32 expression is elevated at the mRNA level upon a variety of CNS insults, including Alzheimer's disease, Duchenne's muscular dystrophy, and acute spinal injury." (PMID 33277362, 2021). "Abnormal expression of TRIM32 has been demonstrated in various human cancer cells, and in the occipital lobe of Alzheimer’s disease patients." (PMID 33999923, 2021). "In addition, TRIM32 participated in many CNS-related diseases, including Alzheimer's disease, autism spectrum disorder (ASD) and attention deficit hyperactivity disorder (ADHD), anxiety and obsessive compulsive disorder." (PMID 34421574, 2021). "In contrast with the elevated TRIM32 expression observed in various pathological conditions, including independently derived tumours, Alzheimer's disease and skeletal muscle subjected to hind-limb suspension, down-regulation of TRIM32 expression was seldom mentioned in the previous studies." (PMID 26884348, 2016).
hepatocellular carcinoma (5 papers, 2018 to 2025). A malignant tumor that arises from hepatocytes. "TRIM32 has been implicated in carcinogenesis, with elevated levels of TRIM32 has been associated with the development of cancer, as increased levels of TRIM32 mRNA have been found in hepatocellular carcinoma, GC, and breast cancer, where it serves as a biomarker for prognosis." (PMID 41163195, 2025). "Cui et al18 found that up‐regulated TRIM32 correlates with enhanced cell proliferation and poor prognosis in hepatocellular carcinoma." (PMID 30079558, 2018). "Moreover, TRIM32 suppressed the apoptosis induced by cisplatin in the hepatocellular carcinoma (HCC) cell line HEp2." (PMID 33935743, 2021). "Moreover, TRIM32 was a significant predictor of the prognosis of hepatocellular carcinoma (HCC), and the overexpression of TRIM32 may induce HCC patients’ resistance to oxaliplatin." (PMID 35756612, 2022).
Anxiety (4 papers, 2015 to 2023). Intense feelings of nervousness, tension, or panic often arise in response to interpersonal stresses. "Finally, we have hints that an impairment of adult neurogenesis caused by loss of TRIM32 results in the deregulation of metabolomic pathways that have been linked to depression and anxiety related behavior." (PMID 25852471, 2015). "TRIM32 has been linked to several human diseases including limb–girdle muscular dystrophy type 2H, Bardet–Biedl syndrome, cancer, autism spectrum disorder, depression, Alzheimer's disease, obsessive compulsive disorder, anxiety, and attention deficit hyperactivity disorder." (PMID 25852471, 2015). "Conversely, Trim32 was found to be upregulated for both male and female high anxiety, Low Activity mice." (PMID 36514243, 2023). "Recent reports have associated TRIM32 with psychiatric disorders, such as MDD, ASD, ADHD, anxiety and obsessive–compulsive disorder (reviewed in48)." (PMID 34267256, 2021). "To identify affected anxiety and depression related pathways, we performed metabolomic analyses from brain tissue of 3 wt and 4 TRIM32 ko mice." (PMID 25852471, 2015). "Using a chronic unpredictable mild stress (CUMS) mouse model that generates anxiety- and depression-like behavior, Ruan and colleagues showed that TRIM32 protein levels are downregulated in the hippocampus under mild stress." (PMID 25852471, 2015). "However, the function of TRIM32 in depression and anxiety is still controversial." (PMID 25852471, 2015). "Although in our TRIM32 ko mice we did not observe any anxiety related phenotypes, in our metabolomics approach we detected several metabolites to be deregulated which previously have been shown to be implicated in anxiety and depression." (PMID 25852471, 2015). "Thus, loss of TRIM32 does not impair exploratory behavior, anxiety-related behavior but leads to increased number of stops in the open field test." (PMID 25852471, 2015). "Most interestingly, other behavioral domains (such as exploratory behavior, anxiety-like behavior, and spatial learning) were not affected by the lack of TRIM32." (PMID 25852471, 2015).
autism spectrum disorder (4 papers, 2021 to 2022). A spectrum of developmental disorders that includes autism, and Asperger syndrome. "An electrophysiology-based genetic screen of 157 E3 ligase-encoding genes at the Drosophila neuromuscular junction identified thin, an ortholog of human tripartite motif-containing 32 (TRIM32), a gene implicated in several neurological disorders, including autism spectrum disorder and schizophrenia." (PMID 35796533, 2022). "It was reported that TRIM32 reduced PI3K‐Akt‐FoxO signalling by promoting plakoglobin‐PI3K dissociation in muscle atrophy, and TRIM32 deficiency was found to cause hypoactive mTOR in autism spectrum disorder mice model." (PMID 34921503, 2022). "In addition to hosting rare copy number variants (CNV) that have been linked to autistic spectrum disorders, ADHD, and OCD by a large GWAS, this locus also contains the astroactin-2 (ASTN2) and tri-component motif protein 32 (TRIM32)." (PMID 34201295, 2021).
breast carcinoma (4 papers, 2020 to 2025). "TRIM32, which is also implicated in breast cancer, is overexpressed in NSCLC, inducing cell proliferation, colony formation, and invasion, and mediating cisplatin chemotherapy resistance through activation of the NF-κB/Bcl-2 signaling pathway." (PMID 41305005, 2025). "A previous report has demonstrated that TRIM32 is overexpressed in breast cancer and promotes the proliferation of breast cancer cells." (PMID 32051827, 2020).
Duchenne muscular dystrophy (4 papers, 2021 to 2023). Duchenne muscular dystrophy (DMD) is a neuromuscular disease characterized by rapidly progressive muscle weakness and wasting due to degeneration of skeletal, smooth and cardiac muscle. "Some, such as Duchenne muscular dystrophy and limb girdle muscular dystrophy 2H, are caused by mutations in genes encoding muscle structural proteins (dystrophin and Trim32, respectively), while others, like myotonic dystrophy, are caused by defects in RNA metabolism." (PMID 33561245, 2021). "This review is focused on understanding the physiological roles of TRIM32 in skeletal muscle, the pathophysiological mechanisms mediated by TRIM32 genetic variants in LGMD2H patients, and the correlations between TRIM32 and Duchenne muscular dystrophy (DMD)." (PMID 37626915, 2023). "Indeed, TRIM32 is selectively upregulated in regenerating fibers derived from Duchenne muscular dystrophy (DMD) or Becker muscular dystrophy (BMD) patients, further highlighting the importance of TRIM32 in muscle growth." (PMID 33802079, 2021). "In addition, genetic variants of TRIM32, animal models of LGMD2H, and correlations between TRIM32 and Duchenne muscular dystrophy (DMD) are described." (PMID 37626915, 2023).
glioma (4 papers, 2021 to 2025). A benign or malignant brain and spinal cord tumor that arises from glial cells (astrocytes, oligodendrocytes, ependymal cells). "A recent study revealed that TRIM32 deficiency enhances the incidence of medulloblastoma formation, as TRIM32 suppresses cerebellar development and tumorigenesis by degrading glioma-associated oncogene/sonic hedgehog signaling." (PMID 34421574, 2021). "Another Group C-VII protein, TRIM32 was reported as being upregulated in glioma tissues." (PMID 36139694, 2022).
lung carcinoma (4 papers, 2020 to 2022). "For example, TRIM32 positively regulates p-STAT3 levels in lung cancer, and TRIM52 promotes SHP2 ubiquitination, consequently inactivating STAT3 signaling in colorectal cancer." (PMID 36288633, 2022). "Previous studies demonstrated that overexpression of TRIM32 could promote proliferation of lung cancer cells by activating JAK2/STAT3 signaling pathway." (PMID 35756612, 2022). "TRIM32 overexpression promotes lung cancer cell proliferation by activating the JAK2/STAT3-signaling pathway, as STAT3 has also been implied in muscle wasting during cancer, it would be interesting to test if TRIM32 also activates this inflammatory pathway in muscles." (PMID 33802079, 2021).
Atrophy (3 papers, 2015 to 2024). Any weakening or degeneration, especially through lack of use. "It seems reasonable to assume that the detection of diglycine modification sites on obscurin and FHL1 indicates that these M-band proteins are degraded by the E3 ubiquitin ligase MURF1 and TRIM32 during early atrophy." (PMID 28546288, 2017). "In a recent study, E3 ubiquitin ligase tripartite motif-containing 32 (TRIM32) was demonstrated to be essential for the selective regrowth of Type 2 fast fibers after hind limb suspension-induced atrophy." (PMID 26257645, 2015).
attention deficit-hyperactivity disorder (3 papers, 2012 to 2022). A disorder characterized by a marked pattern of inattention and/or hyperactivity-impulsivity that is inconsistent with developmental level and clearly interferes with functioning in at least two settings (e.g. at home and at school). "The TRIM32 gene is suggested to be involved in muscle and nervous system development mouse phenotypes and deletions in this gene are also reported in cases with attention deficit hyperactivity disorder." (PMID 23275889, 2012).
ciliopathies (3 papers, 2012 to 2022). "Some ciliopathies are caused by mutations in genes that are primarily associated with non-ciliopathy syndromes (for example, TRIM32/BBS11, NPHP3, and KIF7)." (PMID 23351659, 2012).
colorectal cancer (3 papers, 2022 to 2025). A primary or metastatic malignant neoplasm that affects the colon or rectum. "In our study, we divided the samples into high- and low-TRIM32 expression groups according to the mean expression level of TRIM32 in colorectal cancer tissue samples." (PMID 40507857, 2025). "Building on our previous studies, we utilized Western blotting to assess the expression levels of TRIM32 in multiple colorectal cancer cell lines, including HT29, SW480, SW620, HCT15, and HCT116." (PMID 40507857, 2025). "To further clarify the impacts of TRIM32 and other clinicopathological factors on the prognosis of colorectal cancer patients, we conducted a Cox regression analysis." (PMID 40507857, 2025). "In the present experiment, the impact of TRIM32 on the proliferation of colorectal cancer cells was evaluated by contrasting the quantity, size, and morphological features of the colonies formed by cells in different treatment groups." (PMID 40507857, 2025). "In the context of cancer, TRIM32 was able to promote the proliferation and motility of lung, gastric, squamous cancer cells or contribute to cisplatin resistance in colorectal cancer, whereas the role of TRIM32 in PDAC cells remained unknown." (PMID 34921503, 2022). "However, the mechanism of TRIM32 in colorectal cancer (CRC) is unclear." (PMID 40507857, 2025). "In the realm of colorectal cancer (CRC), some previous studies have preliminarily explored the expression of TRIM32 in CRC tissues." (PMID 40507857, 2025). "The results indicated that there was no statistical difference between changes in TRIM32 expression and the DFS of colorectal cancer patients." (PMID 40507857, 2025).
depression (3 papers, 2015 to 2022). "Depression in general is associated to reduced levels of neurogenesis, while in TRIM32 knock-out mice neurogenesis is increased." (PMID 25852471, 2015). "However, at the same time they demonstrate that a total loss of TRIM32 (knock-out mouse model) protects against depression." (PMID 25852471, 2015). "It seems tempting to speculate that these two effects, in the CUMS depression model in TRIM32 knock-out mice, balance each other leading to a normalized neurogenesis activity." (PMID 25852471, 2015).
endometriosis (3 papers, 2020 to 2026). The growth of functional endometrial tissue in anatomic sites outside the uterine body. "Endometrium, adrenal gland and the brain are among the three leading sites of TRIM32’s expression, lending greater support for its potential involvement in endometriosis and migraine." (PMID 32121467, 2020). "Combining gene-based p-values across endometriosis and migraine, three genes, two (TRIM32 and SLC35G6) of which are at novel loci, were genome-wide significant." (PMID 32121467, 2020). "We delve into the specific shared risk loci, such as TRIM32 and SLC44A4, and demonstrate how they converge on dysregulated biological pathways, notably IL-1, TNF-α, and MAPK/ERK signaling that drive both peripheral inflammation in endometriosis and neuroinflammation in migraine." (PMID 42222530, 2026). "After combining gene-based p-values across endometriosis and migraine GWAS, we found that three genes (ARL14EP, TRIM32, and SLC35G6), were genome-wide significant." (PMID 32121467, 2020). "The remaining two genome-wide significant genes, TRIM32 and SLC35G6, have not been previously reported for endometriosis or migraine, neither are they located at or near established loci for any of the two disorders; hence, they represent two novel genes and susceptibility loci for the two traits." (PMID 32121467, 2020). "Two of these genes (TRIM32, and SLC35G6) have not previously been reported for endometriosis or migraine, nor were they located on or near previously identified loci for any of the two traits—indicating that they represent novel genes and susceptibility loci for both endometriosis and migraine." (PMID 32121467, 2020).
influenza infection (3 papers, 2015 to 2023). "Here we report that in response to influenza infection, TRIM32 targets PB1 for K48-linked ubiquitination." (PMID 26057645, 2015). "DBALIS found that overexpression of TRIM32, STUB1 and FKBP8 reduced influenza infection activity from two to four fold, indicating their role in viral restriction." (PMID 27375580, 2016). "TRIM32 senses IAV infection by interacting with PB1 and translocates with PB1 to the nucleus following influenza infection." (PMID 26057645, 2015). "TRIM32 and STUB1 are genes known to limit influenza infection." (PMID 27375580, 2016).
migraine (3 papers, 2020 to 2026). "We identified at least 3 SNPs in the vicinity of this gene that show the strongest association with both migraine and CTS, all of which alter the expression levels of TRIM32." (PMID 37606917, 2024). "The 2 results, considered together, suggest the importance of TRIM32 in mediating the shared genetics between CTS and migraine." (PMID 37606917, 2024).
sarcopenia (3 papers, 2021 to 2023). Progressive decline in muscle mass due to aging which results in decreased functional capacity of muscles. "Trim32 mutations have been found in limb–girdle muscular dystrophy 2H, and mice knock-out for Trim32 develop premature sarcopenia." (PMID 36430301, 2022). "Moreover, Trim32–/– muscles exhibited features of early sarcopenia signs, such as selective type II fast fiber atrophy." (PMID 36831310, 2023).